EZR (ezrin)
Diseases named in the same sentence as EZR in open-access papers (continued):
Sharing a sentence is not in itself a finding about the gene and the disease.
astrocytoma (3 papers, 2019 to 2023). "Ezrin has also been implicated in invasive behaviour of astrocytomas, and glial activation." (PMID 31382374, 2019). "In this study, we want to show that DNA methylation plays a key regulatory role by which miRNA-204-5p inhibits the invasion and migration of astrocytoma cells by inhibiting the expression of ezrin." (PMID 34723710, 2021). "Here, we showed that miRNA-204-5p plays a vital role in suppressing tumor invasion and migration and ezrin is one of its direct downstream genes in astrocytoma." (PMID 34723710, 2021). "As expected, higher expression levels of ezrin was detected in the astrocytoma tissue samples and astrocytoma cell lines with low miRNA-204-5p expressions compared with their respective controls." (PMID 34723710, 2021). "We have shown in our previous work that miRNA-204-5p inhibits astrocytoma cell migration and invasion and functions as a direct negative regulator of EZRIN gene expression." (PMID 34723710, 2021). "Overall, our study suggests that miRNA-204-5p acts as a tumor suppressor to influence astrocytoma invasion and migration by targeting ezrin and that miRNA-204-5p expression is downregulated by DNA methylation." (PMID 34723710, 2021). "By adjusting the DNA methylation level of the miRNA-204-5p promoter region, we showed that DNA methylation plays a key regulatory role by which miRNA-204-5p inhibits the invasion and migration of astrocytoma cells by inhibiting the expression of ezrin." (PMID 34723710, 2021). "DNA methylation-induced changes in the expression of miRNA-204-5p have a direct effect on the invasion and migration of human astrocytoma cells and that ezrin may be a potential target involved in these effects." (PMID 34723710, 2021). "We speculate that miRNA-204-5p promoter methylation may be relevant to astrocytoma cell migration and invasion by affecting the expression levels of miRNA-204-5p and ezrin." (PMID 34723710, 2021). "Results from our study may greatly facilitate the development of potential therapeutic targets for astrocytoma patients, and further investigations on the roles of ezrin, miRNA-204-5p, and DNA methylation in astrocytoma are needed." (PMID 34723710, 2021). "In summary, this study demonstrates that DNA methylation-induced changes in the expression of miRNA-204-5p have a direct effect on the invasion and migration of human astrocytoma cells and that ezrin may be a potential target involved in these effects." (PMID 34723710, 2021). "High expression of ezrin significantly affects the prognosis of astrocytoma patients." (PMID 34723710, 2021). "Thus, miRNA-204-5p and ezrin might serve as targets to suppress astrocytoma recurrence and metastasis." (PMID 34723710, 2021).
breast invasive ductal carcinoma (3 papers, 2018 to 2022). "They found marked Ezrin protein (Villin) expression in breast invasive ductal carcinoma which was positively associated with axillary lymph node involvement." (PMID 33391377, 2021).
cyst (3 papers, 2015 to 2022). A sac-like closed membranous structure that may be empty or contain fluid or amorphous material. "The overexpression of a phosphorylation-deficient ezrin (T564A) mutant prevented this pronephric cyst formation." (PMID 35328667, 2022). "In addition, the overexpression of either a phosphorylation-deficient (T564A) or phosphorylation-mimetic mutant ezrin (T564D) caused pronephric cyst formation." (PMID 35328667, 2022). "In fact, ezrin knockdown causes prominent hydrocephalus and pronephric cyst formation." (PMID 35328667, 2022). "In pronephric tubules of zebrafish embryos, the knockdown of ELMO, DOCK1, or Rac1 increased ezrin phosphorylation, accompanied by prominent pronephric cyst formation." (PMID 35328667, 2022). "Importantly, fortifying the link between the apical membrane and actin cortex by overexpression of the ezrin/radixin/moesin ortholog ERM-1, significantly rescued cyst formation and ruptures in the pigv-1(qm34) mutant." (PMID 25807459, 2015). "Localization of ezrin at the plasma membrane at a common point between the apposing cells interrupted junction integrity and continuity locally soon after the first cell division (day 1), defining the apical initiation site, a situation analogous to that in MDCK cyst morphogenesis." (PMID 27780871, 2017).
endometrioid carcinoma (3 papers, 2012 to 2022). "Other studies have also indicated that ezrin and moesin are highly expressed at mRNA and/or protein levels in human endometrioid carcinoma tissues and several human endometrial epithelial cancer cell lines, such as RL-95, AN3CA, Ishikawa, HEC-50, and HEC-1-A." (PMID 35456317, 2022).
HIV-1 infection (3 papers, 2018 to 2021). The type species of lentivirus and the etiologic agent of acquired immunodeficiency syndrome (AIDS). "We have previously reported that ezrin expressed in target cells is required for efficient CXCR4-tropic HIV-1 infection." (PMID 32411688, 2020). "Previously, we have reported that expression of ezrin in target cells is required for CXCR4-tropic HIV-1 infection, and expression of ezrin in HIV-1-producing cells is required for infectivity of released HIV-1 particles." (PMID 32411688, 2020). "This study investigates the impact of ezrin phosphorylation in X4-tropic HIV-1 infection and virion release using ezrin mutants." (PMID 30210460, 2018). "Host-cell expression of the ezrin protein is required for CXCR4 (X4)-tropic HIV-1 infection." (PMID 30210460, 2018). "This study investigates the role of ezrin phosphorylation in HIV-1 infection and virion release." (PMID 30210460, 2018). "Among these, focal adhesion proteins are required during early stages of HIV-1 infection, while the ezrin-radixin-moesin (ERM) family members, moesin and ezrin function as negative regulators of early post-entry infection, before or at the initiation of reverse transcription." (PMID 34229718, 2021).
medulloblastoma (3 papers, 2014 to 2020). A malignant, invasive embryonal neoplasm arising from the cerebellum. "Using medulloblastoma cell lines and athymic mice as models, a study reported that Ezrin is localized to filopodia in medulloblastoma cells and promotes filopodia formation as well as in vitro invasion in medulloblastoma." (PMID 33240887, 2020). "Transcriptome sequencing / real time RT-PCR / western blot analysis showed downregulation of RAB22A, M6PR, EZR, EPHB2, upon miR-204 expression in medulloblastoma cells as well." (PMID 30944042, 2019).
metastasis (3 papers, 2012 to 2022). The spread or migration of cancer cells from one part of the body (where they first appeared) to another. "Additionally, Ezrin protein overexpression was significantly correlated with the lymph node metastasis of gastric adenocarcinoma." (PMID 23039327, 2012).
metastatic cancer (3 papers, 2010 to 2022). A carcinoma which has spread from the original site of growth to another anatomic site. "Here we found that the strongly positive rate of Ezrin protein expression was significantly higher in metastatic gastric cancer (91.3%) than it in non-metastatic cancer cases (35.1%) (P < 0.01)." (PMID 23039327, 2012).
neuroblastoma (3 papers, 2008 to 2024). Neuroblastoma (NB) is the most common solid, extracranial childhood tumor. "Using these transfectants, we conducted co-immunoprecipitation assays to determine whether α-actinin or ezrin associated with ICAM-2 and/or actin in transfected neuroblastoma cells." (PMID 18978946, 2008). "Therefore, we postulated that membrane-bound ICAM-2 binds to cytoplasmic ezrin or α-actinin which, in turn, binds to actin to regulate the motility—and hence the metastatic potential—of neuroblastoma cells." (PMID 18978946, 2008). "These suggest that Aβ monomers may promote the differentiation of neuroblastoma SH-SY5Y through activating MAP2 and Ezrin." (PMID 39125907, 2024). "RT-PCR analysis of a panel of neuroblastoma cell lines (data not shown) showed that neuroblastoma cells express two of these linker proteins: ezrin and α-actinin." (PMID 18978946, 2008).
oral cancer (3 papers, 2014 to 2020). "Interestingly, the cytoplasmic ezrin reflects its activated form and, in oral cancer, this pattern of cytoplasmic ezrin has been associated with invasive phenotype and more aggressive behavior of malignant cells." (PMID 25480364, 2014). "Ezrin overexpression has been observedin a subpopulation of an oral cancer cell linewhich was CD44+, as a marker of cancer stemcells." (PMID 28670517, 2017). "In oral cancer cells, SNAIL was previously associated with changes in RHO activity and phosphorylation of EZRIN-RADIXIN-MOESIN family, but no precise mechanism was described." (PMID 32664538, 2020).
retinal degeneration (3 papers, 2022 to 2025). Degeneration of the retina. "Consistently, Medaka fish deficient for Ezrin exhibit defective endo-lysosomal pathway, attributable to the compromised EGFR/AKT signaling, ultimately leading to retinal degeneration." (PMID 39937579, 2025). "Therefore, we investigated the role of RPE cells in retinal degeneration of Mdm1−/− mice by immunofluorescence staining with Ezrin, an apical marker of the RPE cells due to its high abundance in apical microvilli." (PMID 36171205, 2022). "Consistent with the role of the Ezrin/EGFR/TSC complex axis in lysosomal biogenesis and function, alteration of this molecular network alters autophagy in vivo in Medaka fish, resulting in retinal degeneration." (PMID 39937579, 2025).
thyroid carcinoma (3 papers, 2019 to 2022). "The overall sensitivity, specificity of ezrin and phospho-ezrin for the association between all thyroid carcinomas and FA was calculated." (PMID 30996241, 2019). "As an invasive protein, the impact of ezrin in invasion of thyroid carcinoma is minimally investigated." (PMID 30996241, 2019). "Other signalling cascades phosphorylating ezrin in thyroid carcinoma during estrogen exposure has to be identified." (PMID 30996241, 2019). "Comprehensive theory explaining the relationship between estrogen (E2) and ezrin in metastasis of thyroid cancer remains non-elicited." (PMID 30996241, 2019). "Using proteomics, we previously characterized an intracellular signaling pathway derived from SRC kinase that acts through the small GTPase RAC1 to recruit and bind the actin-anchoring adaptor EZRIN to NIS, regulating its retention at the PM of both non-transformed and cancer thyroid cells." (PMID 36358781, 2022).
urothelial bladder cancer (3 papers, 2014 to 2023). "Reduced membranous expression of the cytoskeleton-associated protein ezrin has previously been demonstrated to correlate with poor prognosis in urothelial bladder cancer in several independent studies." (PMID 25278252, 2014). "In summary, the results from this study demonstrate that reduced membranous ezrin expression in urothelial bladder cancer is associated with more advanced tumours and a reduced survival." (PMID 24885195, 2014). "The results from this study demonstrate that loss of membranous ezrin expression in urothelial bladder cancer is strongly associated with a more aggressive tumour phenotype; i.e. higher grade and more advanced tumour stage, and an impaired survival." (PMID 24885195, 2014). "The results from this study validate previous findings of reduced membranous ezrin expression in urothelial bladder cancer being associated with unfavourable clinicopathological characteristics and an impaired survival." (PMID 24885195, 2014). "Thus, the results from our study further validate previous findings of strong significant associations between loss of membranous ezrin expression and more advanced T-stage and high tumour grade in urothelial bladder cancer." (PMID 24885195, 2014). "In the present study, we examined the prognostic significance of ezrin expression in urothelial bladder cancer in a total number of 442 tumours from two independent patient cohorts." (PMID 24885195, 2014). "Despite use of different antibodies for detection of ezrin expression in the two previous studies and the present, the results were concordant, which further supports the utility of ezrin as a prognostic and, potentially treatment predictive, biomarker in urothelial bladder cancer." (PMID 24885195, 2014). "In light of the apparently contrasting prognostic value and intercorrelation of ezrin and PODXL expression in urothelial bladder cancer, it will be of interest to investigate the existence of a negative functional cooperativity between these proteins in this cancer form." (PMID 24885195, 2014).
uveal melanoma (3 papers, 2008 to 2022). A melanoma derived from melanocytes of the uveal tract. "Disease progression in uveal malignant melanoma is associated with a relatively high level of expression of the ERM cytoskeletal linker protein ezrin." (PMID 18978946, 2008).
acute myeloid leukemia (2 papers, 2022 to 2026). Acute myeloid leukemia (AML) is a group of neoplasms arising from precursor cells committed to the myeloid cell-line differentiation. "These same ezrin inhibitors have recently been shown to reduce cell viability and cell-cycle progression of acute myeloid leukemia (AML) cells and may also demonstrate synergy with chemotherapy and/or targeted therapies used to treat AML." (PMID 36923551, 2022).
age-related macular degeneration (2 papers, 2024 to 2025). Age-related loss of vision in the central portion of the retina (macula), secondary to retinal degeneration. "Upregulation of Ezrin has been shown to induce an age-related macular degeneration-like phenotype in miR-211−/− mice, where light-mediated cell clearance is completely abolished." (PMID 39937579, 2025). "Additionally, human RPE cells isolated from age-related macular degeneration donors have demonstrated decreased levels of miR-184, impacting RPE phagocytic function through enhanced expression of ezrin." (PMID 38997088, 2024).
allergic asthma (2 papers, 2015 to 2022). A asthma with a basis in a pathological type I hypersensitivity reaction. "After allergen exposure, significant increases in serum levels of ezrin were observed in patients with allergic asthma." (PMID 35807067, 2022). "Furthermore, the upregulated genes (PDPK1, EZR, MYO6, CDC42BPA, OPHN1, ARF6 and WASL) identified in the present study that were enriched in the actin filament-based process require further study in order to determine whether they may be used as potential biomarkers of allergic asthma." (PMID 25633562, 2015).
anaemia (2 papers, 2010 to 2015). "Inactivation of the ezrin protein, leading to ineffective erythropoiesis and dyserythropoiesis, appears to be a key event resulting in the development of severe anaemia." (PMID 25889165, 2015). "Plasmodium vivax is able to enter bone marrow, as previously reported, and parasites or its products bind to erythroid progenitor cells, resulting in decreased ezrin phosphorylation, leading to suppression of erythroid development, and ultimately anaemia." (PMID 25889165, 2015). "Importantly, the red cell distribution width (RDW) of RBCs was increased in ezrin−/− mice, suggesting that the time of erythropoiesis was shortened to counteract anemia." (PMID 20806059, 2010). "Although measurements of the hematocrit from ezrin−/− mice were not consistent with anemia, inaccurate hematocrit and hemoglobin counts could be caused by dehydration." (PMID 20806059, 2010). "The lack of splenic RBCs in ezrin−/− mice suggests the presence of severe anemia." (PMID 20806059, 2010).
atherosclerosis (2 papers, 2020 to 2023). A disease characterized by the build-up of fatty material and calcium deposition in the arterial wall resulting in partial or complete occlusion of the arterial lumen. "SLC9A3R1 (also known as NHERF1 and EBP50 is a scaffolding protein of ezrin), also enriched in RA-pEVs, is known to be involved in the regulation of smooth muscle cell migration and in atherosclerosis, a disorder with pain and fatigue as comorbidity symptoms." (PMID 38274452, 2023).
autoimmune disease (2 papers, 2022 to 2024). A disorder resulting from loss of function or tissue destruction of an organ or multiple organs, arising from humoral or cellular immune responses of the individual to their own tissue constituents. "Many of these genes have either known roles in Treg differentiation, stability and function (CD48, IL6ST, EZR, ELMO1, IL18R1), or altered expression in human Treg in autoimmune disease (SLAMF1, ANKRD55, TAGAP)." (PMID 35773720, 2022).
bladder tumors (2 papers, 2013 to 2014). "The proteomic approach identified differential expression of proteins previously linked with aggressive clinical outcome in bladder tumors: gelsolin, moesin, Ezrin, caveolin, Filamin A." (PMID 23308193, 2013). "The prognostic value of membranous ezrin was confirmed in both unadjusted (HR = 2.51, 95% CI 1.52-4.17) and adjusted (HR = 1.69, 95% CI 1.00-2.85), and these associations were slightly more significant when only bladder tumours were included in the analysis." (PMID 25278252, 2014). "Of note, in contrast to previous studies related to the prognostic values of ezrin, the present study also included a small subset of non-bladder tumours." (PMID 25278252, 2014). "In bladder tumours only, cytoplasmic ezrin expression was prognostic in unadjusted but not in adjusted analyses (data not shown)." (PMID 25278252, 2014).
carcinoma in situ (2 papers, 2018 to 2020). "We found that ERK and ezrin were significantly overexpressed in invasive squamous cell carcinoma (SCC) compared to carcinoma in situ (CIS)." (PMID 30344309, 2018). "Immunohistochemical staining showed that ERK and ezrin expressions were significantly higher in invasive squamous cell carcinoma than in carcinoma in situ." (PMID 30344309, 2018).